LINC01970 (long independently transcribed non-coding RNA 1970)
Gene: Long non-coding RNA gene on chromosome 17 (82,290,046 to 82,292,814, reverse strand). Ensembl gene ENSG00000265692.
Diseases named in the same sentence as LINC01970 in open-access papers:
LINC01970 is named in the same sentence as 2 diseases in open-access papers, as found by Europe PMC text mining. Sharing a sentence is not in itself a finding about the gene and the disease. The quoted sentences say what the papers report.
Cirrhosis (1 paper, 2020). A chronic disorder of the liver in which liver tissue becomes scarred and is partially replaced by regenerative nodules and fibrotic tissue resulting in loss of liver function. "Univariate analysis identified the following 11 lncRNAs as significantly correlated with RFS of patients with cirrhosis: SH3RF3-AS1, AC104117.3, AC136475.3, LINC00239, MRPL23-AS1, LINC00494, LINC01970, MEG3, Z93930.3, MIR9-3HG and TRBV11-2." (PMID 32592379, 2020).
Smith-Magenis syndrome (1 paper, 2019). Smith-Magenis syndrome (SMS) is a complex genetic disorder characterized by variable intellectual deficit, sleep disturbance, craniofacial and skeletal anomalies, psychiatric disorders, and speech and motor delay. "We have restored the official and standardized names, LINC01970 and SMCR2 (Smith-Magenis syndrome Chromosome Region, candidate 2), for the two lncFASN and lncSREBF1 genes respectively." (PMID 31752679, 2019).